FABP12 (fatty acid binding protein 12)
Description:
May play a role in lipid transport.
Tractability: No criterion of Open Targets' tractability assessment is met for any kind of drug.
Gene: Protein-coding gene on chromosome 8 (81,524,974 to 81,590,139, reverse strand). Ensembl gene ENSG00000197416.
Pathways (Reactome):
Metabolism: Triglyceride catabolism
Gene Ontology:
Molecular function: fatty acid binding; lipid transporter activity; lipid binding
Biological process: fatty acid transport; triglyceride catabolic process
Cellular component: cytosol; nucleus
Genetic constraint (gnomAD): Loss-of-function variants: 4 observed, 4.64 expected, observed/expected ratio (o/e) 0.86, 90% interval 0.42 to 1.75. That is too few expected variants to judge how well the gene tolerates losing a copy. Missense variants: 82 observed, 73.99 expected, observed/expected ratio (o/e) 1.11, 90% interval 0.93 to 1.33. Synonymous variants: 28 observed, 24.77 expected, observed/expected ratio (o/e) 1.13, 90% interval 0.84 to 1.55.
Homologues: Orthologues: chimpanzee FABP12 (99% identical), rabbit FABP12 (78% identical), mouse Fabp12 (76% identical), dog FABP12 (71% identical), guinea pig FABP12 (64% identical), rat Fabp12 (64% identical), macaque FABP12 (60% identical), zebrafish fabp4b (42% identical), zebrafish fabp4a (39% identical), Drosophila melanogaster fabp (36% identical), Caenorhabditis elegans lbp-8 (33% identical), Caenorhabditis elegans lbp-7 (31% identical), and 2 more. Paralogues in human: PMP2 (62% identical), FABP9 (54% identical), FABP4 (52% identical), FABP3 (49% identical), FABP5 (48% identical), FABP7 (46% identical), RBP7 (34% identical), CRABP2 (33% identical), RBP1 (32% identical), RBP2 (31% identical), CRABP1 (31% identical), RBP5 (30% identical), and 3 more.
Diseases named in the same sentence as FABP12 in open-access papers:
FABP12 is named in the same sentence as 6 diseases in open-access papers, as found by Europe PMC text mining. Sharing a sentence is not in itself a finding about the gene and the disease. The quoted sentences say what the papers report.
prostate carcinoma (5 papers, 2016 to 2025). A carcinoma that arises from epithelial cells of the prostate gland. "Clinical data analysis shows that high expression of FABP12 is significantly associated with poor prognosis in prostate cancer patients." (PMID 40717587, 2025). "FABP12 promotes migration and invasion of prostate cancer (PCa) cells by activating the PPARγ signaling pathway, inducing epithelial-mesenchymal transition (EMT)." (PMID 40717587, 2025). "To further document the role of FABP12 in docetaxel-mediated apoptotic cell death, we examined the effect of ectopic FABP12 expression on a second prostate cancer cell line, hormone-insensitive DU145." (PMID 39273616, 2024). "Fatty acid-binding protein 12 (FABP12) amplification in prostate cancer models leads to PPARγ activation and the concurrent induction of fatty acid uptake, FAO, and EMT." (PMID 38002286, 2023). "FABP12 plays a central role in prostate cancer metastasis and chemo-resistance by regulating lipid metabolism, EMT, and apoptosis-resistance, and may also participate in carcinogenesis through gene amplification in liver cancer." (PMID 40717587, 2025).
metastatic tumors (3 papers, 2020 to 2024). "Three cohorts that consisted mainly of patients with metastatic disease (> 80% of the whole population) showed frequencies of FABP12 amplification ranging from 17% to 30%." (PMID 33031638, 2020). "We recently found that FABP12, whose expression is markedly induced in metastatic tumor tissues from both PCa patients and a xenograft mouse model, promotes lipid accumulation in the form of lipid droplets in PCa cells." (PMID 33352874, 2020). "The FABP12 signal was considerably weaker in primary tumors compared to metastatic tumors." (PMID 33031638, 2020). "This idea is in keeping with our observation that FABP12 levels are induced in metastatic tumors derived from a mouse xenograft PC3 model and support the ‘Go‐or‐Grow’ hypothesis proposed for tumor invasion." (PMID 33031638, 2020). "Thus, elevation of FABP12 in our xenograft metastatic tumors mimics the preferential expression of FABP12 in metastatic tumors observed in PCa patient cohorts." (PMID 33031638, 2020). "We examined FABP12 RNA levels in four human PCa cell lines (VCaP, PC3, DU145, LNCaP) derived from metastatic tumors using semiquantitative PCR." (PMID 33031638, 2020). "Targeting FABP12, as opposed to the more broadly-expressed Survivin, Slug or PPARγ, especially in patients with advanced or metastatic tumors, may therefore be of added benefit due to reduced side effects." (PMID 39273616, 2024). "Notably, there was a much higher negative correlation between FABP12 and CDH1 mRNA levels in metastatic tumors (r = −0.66, P = 0.002) than in primary tumors (r = −0.25, P = 0.004)." (PMID 33031638, 2020).
hepatocellular carcinoma (1 paper, 2025). A malignant tumor that arises from hepatocytes. "In hepatocellular carcinoma (HCC), FABP12 forms a gene cluster with FABP4, FABP5, FABP8, and FABP9, which is frequently co-amplified." (PMID 40717587, 2025).
retinoblastoma (1 paper, 2022). A malignant tumor that originates in the nuclear layer of the retina. "FABP-12 is present in human retinoblastoma cell lines, rodent retina, and testes." (PMID 36144237, 2022).
cancer (4 papers, 2020 to 2025). A tumor composed of atypical neoplastic, often pleomorphic cells that invade other tissues. "FABP12 expression promotes properties associated with cancer progression such as EMT conversion, invasion, and metastasis." (PMID 33031638, 2020). "In pan-cancer analyses, FABP8 forms a gene cluster with FABP4, FABP5, FABP9, and FABP12, which frequently undergo co-amplification in various cancers." (PMID 40717587, 2025). "Future research should explore the role of FABP12 in other cancers (e.g., colorectal and breast cancer) and develop specific inhibitors." (PMID 40717587, 2025). "Recent studies indicate that FABP12 plays an important role in cancer progression, particularly in metastasis and chemoresistance." (PMID 40717587, 2025). "As Survivin is known to regulate chemodrug sensitivity in cancer cells, we investigated whether Survivin could be a downstream effector of FABP12 in modulating cellular response to docetaxel." (PMID 39273616, 2024). "Except for FABP5, mRNA levels of FABP12, FABP4, FABP9 and FABP8 were upregulated in cancers with higher Gleason scores." (PMID 33352874, 2020).
tumor (4 papers, 2020 to 2025). "Based on our findings, we propose that increased FABP12 expression represents one of the major adaptations of PCa cells required to trigger a pro‐invasive molecular pathway and to satisfy the increased energy demands associated with tumor expansion and metastasis (Graphical abstract)." (PMID 33031638, 2020). "We observed FABP12 in the cytoplasm (black arrowhead), nucleus (arrow), and cell processes (white arrowhead) of the metastatic tumor tissues." (PMID 33031638, 2020). "We also observed a striking increase in FABP12 transcript levels in PC3‐derived metastatic tumor tissue compared to PC3 parental cells." (PMID 33031638, 2020). "To investigate a possible role for FABP12 in metastasis, we immunostained primary and metastatic mouse PC3 xenograft tumor tissues with anti‐FABP12 antibody." (PMID 33031638, 2020). "However, emerging evidence also supports the relevance of less characterized subtypes (e.g., FABP2, FABP8, FABP12) in tumor biology." (PMID 40717587, 2025). "For example, inhibiting FABP12 or blocking its interaction with PPARγ/Slug may reverse drug resistance and delay tumor progression." (PMID 40717587, 2025). "We have previously shown that the FABP12-PPARγ pathway in PCa cells triggers epithelial-to-mesenchymal transition (EMT), a critical process involved in tumor progression, metastatic transformation and treatment resistance." (PMID 39273616, 2024). "However, mRNA expression levels of FABP1, FABP2, FABP5, FABP6, FABP7, FABP9, or FABP12 did not significantly differ in different tumor stages in CRC patients." (PMID 34680577, 2021).